STX1A (syntaxin 1A)
Description:
Plays an essential role in hormone and neurotransmitter calcium-dependent exocytosis and endocytosis. Part of the SNARE (Soluble NSF Attachment Receptor) complex composed of SNAP25, STX1A and VAMP2 which mediates the fusion of synaptic vesicles with the presynaptic plasma membrane. STX1A and SNAP25 are localized on the plasma membrane while VAMP2 resides in synaptic vesicles. The pairing of the three SNAREs from the N-terminal SNARE motifs to the C-terminal anchors leads to the formation of the SNARE complex, which brings membranes into close proximity and results in final fusion. Participates in the calcium-dependent regulation of acrosomal exocytosis in sperm. Also plays an important role in the exocytosis of hormones such as insulin or glucagon-like peptide 1 (GLP-1) (By similarity).
Synonyms: STX1; HPC-1; p35-1; SYN1A
Tractability: Antibody: UniProt places it where antibodies can reach, with high confidence; its Gene Ontology location is reachable by antibodies, with high confidence; UniProt predicts a signal peptide or a membrane-spanning region. PROTAC: UniProt records ubiquitination sites on it; its protein half-life has been measured.
Gene: Protein-coding gene on chromosome 7 (73,699,205 to 73,719,691, reverse strand). Ensembl gene ENSG00000106089.
Subcellular location: Cytoplasmic vesicle, secretory vesicle, synaptic vesicle membrane; Synapse, synaptosome; Cell membrane; Secreted (Isoform 2)
Subcellular location (Human Protein Atlas): Vesicles; Nuclear membrane
Pathways (Reactome):
Neuronal System: Acetylcholine Neurotransmitter Release Cycle; Dopamine Neurotransmitter Release Cycle; GABA synthesis, release, reuptake and degradation; Glutamate Neurotransmitter Release Cycle; Neurexins and neuroligins; Norepinephrine Neurotransmitter Release Cycle; Serotonin Neurotransmitter Release Cycle
Developmental Biology: LGI-ADAM interactions
Disease: Toxicity of botulinum toxin type C (botC)
Immune System: Other interleukin signaling
Metabolism: Regulation of insulin secretion
Metabolism of proteins: Insulin processing
Protein localization: Insertion of tail-anchored proteins into the endoplasmic reticulum membrane
Sensory Perception: Sensory processing of sound by inner hair cells of the cochlea
Gene Ontology:
Molecular function: chloride channel inhibitor activity; identical protein binding; kinase binding; protein binding; SNARE binding; ATP-dependent protein binding; calcium channel inhibitor activity; calcium-dependent protein binding; myosin binding; myosin head/neck binding; protein carrier chaperone; protein-containing complex binding; protein-macromolecule adaptor activity; SNAP receptor activity; transmembrane transporter binding
Biological process: protein sumoylation; secretion by cell; synaptic vesicle endocytosis; synaptic vesicle exocytosis; vesicle fusion; exocytosis; neurotransmitter secretion; positive regulation of calcium ion-dependent exocytosis; positive regulation of catecholamine secretion; positive regulation of norepinephrine secretion; regulation of insulin secretion; hormone secretion; insulin secretion; intracellular protein transport; modulation of excitatory postsynaptic potential; positive regulation of excitatory postsynaptic potential; positive regulation of exocytosis; positive regulation of neurotransmitter secretion; protein localization to membrane; regulated exocytosis; regulation of dopamine secretion; regulation of exocytosis; regulation of synaptic vesicle priming; response to gravity; SNARE complex assembly; and 2 more
Cellular component: neuron projection; plasma membrane; SNARE complex; synaptobrevin 2-SNAP-25-syntaxin-1a complex; cytosol; presynaptic membrane; synaptic vesicle membrane; voltage-gated potassium channel complex; actomyosin; axon; cytoplasmic side of membrane; extracellular region; glutamatergic synapse; membrane; nuclear membrane; postsynaptic density membrane; presynaptic active zone membrane; protein-containing complex; Schaffer collateral - CA1 synapse; secretory granule; synapse; synaptic vesicle; synaptobrevin 2-SNAP-25-syntaxin-1a-complexin I complex; synaptobrevin 2-SNAP-25-syntaxin-1a-complexin II complex
Genetic constraint (gnomAD): Loss-of-function variants: 4 observed, 35.57 expected, observed/expected ratio (o/e) 0.11, 90% interval 0.054 to 0.26. The upper end of that interval is the gene's LOEUF score, 0.26, which puts it in group 1 of 6, group 1 being the genes least tolerant of losing a copy. Missense variants: 250 observed, 411.74 expected, observed/expected ratio (o/e) 0.61, 90% interval 0.55 to 0.67. Synonymous variants: 135 observed, 152.7 expected, observed/expected ratio (o/e) 0.88, 90% interval 0.77 to 1.02.
Homologues: Orthologues: chimpanzee STX1A (100% identical), macaque STX1A (99% identical), guinea pig STX1A (99% identical), rat Stx1a (99% identical), mouse Stx1a (98% identical), rabbit STX1A (95% identical), tropical clawed frog stx1a (93% identical), pig STX1A (83% identical), dog STX1A (78% identical), Drosophila melanogaster Syx1A (69% identical), zebrafish stx1a (66% identical), Caenorhabditis elegans unc-64 (65% identical). Paralogues in human: STX1B (83% identical), STX2 (64% identical), STX3 (63% identical), STX4 (46% identical), STX11 (30% identical), STX19 (30% identical), STX5 (28% identical), STX12 (23% identical), STX16 (23% identical), STX7 (21% identical), STX17 (21% identical), TSNARE1 (15% identical).
Diseases named in the same sentence as STX1A in open-access papers:
STX1A is named in the same sentence as 137 diseases in open-access papers, as found by Europe PMC text mining. Sharing a sentence is not in itself a finding about the gene and the disease. The quoted sentences say what the papers report.
hemolytic-uremic syndrome (45 papers, 2003 to 2026). Acute kidney injury associated with microangiopathic hemolytic anemia and thrombocytopenia. "STEC strains carrying stx1a and/or stx2a are often associated with human diseases, and stx2a-positive strains are most frequently associated with severe diseases, including haemolytic colitis and haemolytic uraemic syndrome." (PMID 37055811, 2023). "Among these subtypes, stx2a and stx2c are proposed to be associated with high virulence and the ability to cause hemolytic-uremic syndrome (HUS), while stx2d, stx2e, stx1a, and stx1c occurred in milder or asymptomatic infections." (PMID 31783837, 2019). "In humans, ST101 strains were already reported in a patient with hemolytic uremic syndrome (HUSEC) and in nonbloody diarrhea related to a Stx1a-producing E. coli strain." (PMID 32486334, 2020).
autism (16 papers, 2010 to 2023). Persistent deficits in social interaction and communication and interaction as well as a markedly restricted repertoire of activity and interest as well as repetitive patterns of behavior. "We assembled eight individuals harboring ultra rare variants in STX1A who present with a spectrum of intellectual disability, autism and epilepsy." (PMID 36564538, 2023). "STX1A (Syntaxin 1A (brain)) encodes a protein involved in the regulation of serotonergic and GABAergic systems and its expression is altered in autism." (PMID 31323913, 2019). "Many of these variants occur in regulatory regions, including a functionally-relevant SNP located in an intron of syntaxin 1a, a gene that regulates neurotransmitter release and that has been implicated in human autism." (PMID 30337532, 2018). "Syntaxin 1A (STX1A) encodes a protein involved in regulation of serotonergic and GABAergic systems and its expression is altered in autism." (PMID 24548729, 2014). "Moreover, the authors showed that another autism-causing rare variant in the syntaxin 1A gene (STX1A), which converts Arg26 to glutamine (STX1A R26Q), disrupts the molecular mechanisms of reverse transport of DA." (PMID 26137546, 2015). "A dysregulation of STX1A expression has been reported in high functioning autism and Asperger syndrome." (PMID 31323926, 2019). "The role of Stx1A in neurotransmitter release is also supported by studies reporting a possible involvement of Stx1A in the pathophysiology of autism with Stx1A mRNA expression levels being significantly higher in autistic patients compared to controls." (PMID 27199730, 2016). "Gene expression studies have shown that high functioning autism patients has increased expression of STX1A compared to normal cases." (PMID 23521751, 2013). "The third line of evidence is that syntaxin 1A protein levels are increased in autism and decreased in prefrontal cortical neurons in persons with advanced Alzheimer disease (ELISA, t-test p = 0.0003), along with other presynaptic proteins." (PMID 20422020, 2010). "The observation of autistic symptoms in mice is another line of evidence that nonfunctional STX1A-variants rather cause a phenotype of autism and intellectual disability in humans." (PMID 36564538, 2023). "In high-functioning autism, increased syntaxin 1A expression was observed." (PMID 31890034, 2019). "Furthermore, the STX1A gene, which is located at the chromosome 7q11.23, has been found duplicated in patients with speech delay and autism spectrum behaviors." (PMID 27199730, 2016). "A possible role for STX1A in the development of autism has previously been suggested." (PMID 24548729, 2014).
Williams syndrome (9 papers, 2010 to 2024). "Epilepsy is also rare in individuals with Williams-Beuren-Syndrome, who often lack one allele of STX1A, and in whom differences in transcript levels of STX1A have been shown to account for 15.6% of cognitive variation." (PMID 36564538, 2023). "The human STX1A gene is situated on chromosome 7q11.2, and the deletion of a 1 centimorgan region on this chromosome, encompassing the STX1A gene, is associated with Williams syndrome, characterized by cognitive phenotypes, cardiovascular anomalies, and visual impairment." (PMID 38799985, 2024). "The expression levels of STX1A in patient-derived lymphoblastoid cell lines explain 15.6% cognitive variation in patients with Williams Syndrome." (PMID 30349450, 2018). "Since the deleted region on chromosome 7q11.2 in Williams syndrome patients encompasses more genes than just STX1A, reproducing the visual phenotype in a mouse model might require the deletion of additional genes." (PMID 38799985, 2024). "And STX1A may be involved in Williams-Beuren syndrome and Parkinson's disease." (PMID 36157213, 2022). "STX1A is a component of the presynaptic SNARE complex and located in the genome region that is responsible for Williams Syndrome characterized by intellectual or learning disability." (PMID 30349450, 2018).
Alzheimer disease (8 papers, 2010 to 2024). A progressive, neurodegenerative disease characterized by loss of function and death of nerve cells in several areas of the brain leading to loss of cognitive function such as memory and language. "Syntaxin 1A reportedly interacted specifically with intracellular β-amyloid monomers and oligomers in Alzheimer’s disease pathogenesis." (PMID 37190563, 2023). "STX1A expression has been correlated with Williams's syndrome, cystic fibrosis and Alzheimer's disease." (PMID 26673618, 2016). "Through co-expression modular analysis, we identified that the genes diminished in Alzheimer’s disease are most enriched in module 1 (M1) that contains SNARE-binding complex genes, including the core SNARE genes, SNAP-25, STX1A and VAMP2." (PMID 34423299, 2021). "Many of the SNARE complex genes involved in presynaptic vesicle exocytosis were significantly downregulated in Alzheimer’s disease, including SNAP-25, STX1A, SYT1 and VAMP2, while STX2, SYN1 and VAMP3 were not changed." (PMID 34423299, 2021).
diarrhoea (7 papers, 2008 to 2024). "Stx1A and Stx2A are key virulence factors in EHEC O157:H7, playing a pivotal role in the development of hemorrhagic diarrhea and HUC by disrupting protein synthesis in eukaryotic cells." (PMID 38674854, 2024). "All strains from HUS cases harboured stx2a and eae, with or without stx1a, while strains from diarrhoea cases carried exclusively stx1a and eae genes." (PMID 29183554, 2017). "Overall, cases infected with strains carrying stx1a reported bloody diarrhoea more frequently than those without (77.5 % versus 61.8 %, P = 0.001) leading to the hypothesis that possession of stx1a in strains of sublineage IIc leads to higher rates of bloody diarrhoea." (PMID 28348814, 2015).
epilepsy (6 papers, 2019 to 2024). A brain disorder characterized by episodes of abnormally increased neuronal discharge resulting in transient episodes of sensory or motor neurological dysfunction, or psychic dysfunction. "In this study, we delineate a novel STX1A-related neurodevelopmental disorder with or without epilepsy based on two different pathogenic mechanisms and inheritance models." (PMID 36564538, 2023). "Therefore, different lines of evidence support a causal role of ultra rare variants in STX1A to be causative of a neurodevelopmental disorder with or without epilepsy." (PMID 36564538, 2023). "Our description of a STX1A-related neurodevelopmental disorder with or without epilepsy thus expands the group of rare diseases called SNAREopathies." (PMID 36564538, 2023). "Overall, we show for the first time that syntabulin transits more STX1B (but not STX1A) to the excitatory/inhibitory presynaptic membrane in epilepsy, suppressing neuronal hyperexcitability." (PMID 37349285, 2023). "In our study, the p.His16Arg mutant has little effect on the interaction with either closed or open form of STX1A, and this helps to explain why all the affected individuals have no other neurological dysfunction such as epilepsy." (PMID 33251218, 2020). "Here, using biochemical, behavioral, and electrophysiological approaches, we show that syntabulin plays a protective role in epilepsy by interacting with STX1B, but not STX1A, and mediating its delivery to the synapse." (PMID 37349285, 2023).
glioblastoma (6 papers, 2015 to 2022). The most malignant astrocytic tumor (WHO grade IV). "We used data from the GEO and TCGA databases and identified five genes (ITGA5, MMP9, PTPRN, PTX3, and STX1A) that could affect the survival rate of glioblastoma patients and that were differentially expressed between glioblastoma patients and non-tumors groups." (PMID 33767729, 2021). "Furthermore, it was recently described that STX1A inhibition promotes glioblastoma tumor growth." (PMID 26673618, 2016). "Additionally, a prior study has shown that blocking the SNARE protein Stx1 via three distinct methods, including STX1A knockdown, consistently results in a marked slowing of the growth of glioblastoma tumors in an orthotopic mouse model." (PMID 36313669, 2022).
schizophrenia (5 papers, 2016 to 2024). A major psychotic disorder characterized by abnormalities in the perception or expression of reality. "Interestingly, Ser14-phosphorylated STX1a has also been found to be correlated with schizophrenia, showing a 25% reduction, corresponding with a decrease in protein kinase CK239." (PMID 31073146, 2019).
Parkinson disease (4 papers, 2009 to 2023). A progressive degenerative disorder of the central nervous system characterized by loss of dopamine producing neurons in the substantia nigra and the presence of Lewy bodies in the substantia nigra and locus coeruleus. "Similar to Parkinson's disease, the relationship between STX1A and central nervous system diseases is increasingly noticed." (PMID 36157213, 2022). "STX1A is a gene that may be involved Parkinson's disease as it translates to proteases located in brain tissue." (PMID 19811675, 2009).
Asperger syndrome (3 papers, 2014 to 2019). "In this study, the association between three single nucleotide polymorphisms (SNPs) (rs4717806, rs941298 and rs6951030) in STX1A gene and Asperger syndrome (AS) were tested in 650 controls and 479 individuals with AS, all of Caucasian ancestry." (PMID 24548729, 2014).
cognitive decline (3 papers, 2018 to 2023). "Data from our exploratory study revealed that both STX1A and Rab3A proteins were differentially expressed in the hippocampus of old samples, allowing us to hypothesize a potential correlation between aging, Aβ aggregates and cognitive decline in cattle." (PMID 37965495, 2023).
migraine (3 papers, 2012 to 2023). "Recently, variants in the SNARE genes VAMP2, SNAP25 and STX1A have been studied as potential risk factors in several neurological disorders, including migraine." (PMID 37380951, 2023). "Various SNPs were investigated to confirm the involvement of the STX1A gene in migraine susceptibility." (PMID 27191890, 2016). "All these studies support the role of the STX1A gene as a putative risk factor for migraine." (PMID 27191890, 2016). "Additionally, in our sample we found an enrichment of the G allele of rs6951030 in the STX1A gene for female migraineurs only, which reinforces a gender-specific susceptibility in migraine." (PMID 23185642, 2012).
Obesity (3 papers, 2018 to 2023). Accumulation of substantial excess body fat. "Two genes related to obesity, STX1A and RFC2, map to this CNV interval." (PMID 29441128, 2018).
attention deficit-hyperactivity disorder (2 papers, 2018 to 2022). A disorder characterized by a marked pattern of inattention and/or hyperactivity-impulsivity that is inconsistent with developmental level and clearly interferes with functioning in at least two settings (e.g. at home and at school). "Recent studies have shown that mutations or deletions of STX1A are related to human neuropsychological diseases, such as autism spectrum disorder and attention deficit hyperactivity disorder." (PMID 35379245, 2022).
bladder cancer (2 papers, 2018 to 2019). "According to the pathological gradingof bladder cancer, the expression of STX1A was highly increasedin the high grade invasive tumors with distant metastasis." (PMID 30672978, 2019). "In this study, we analyzedthe relative expression of the STX1A and VAMP2(SYB2) for their possible association in the progressionand metastasis of bladder cancer." (PMID 30672978, 2019). "Therefore, we aimed to determine thedifference in expression of STX1A and VAMP2 inrelation to tumor grades and pathological stages in bladder cancer." (PMID 30672978, 2019).